IRF2 (interferon regulatory factor 2)
Diseases named in the same sentence as IRF2 in open-access papers (continued):
Sharing a sentence is not in itself a finding about the gene and the disease.
tumor (continued). "The immunohistochemical scores showed positive correlations between AMER-1 and IRF-2 scores, both in TMA specimens (r = 0.58, P < 0.001) and xenografted tumor tissues (r = 0.59, P < 0.001)." (PMID 35115027, 2022). "We first detected the mRNA level of IRFs in PC, revealing that the level of IRF2, IRF6, IRF7, IRF8 and IRF9 were elevated in tumor tissues in PC." (PMID 35012444, 2022). "Upregulated miR-18a expression decreases interferon regulatory factor 2 (IRF2) activity leading to decreased cell apoptosis and enhanced cell proliferation in NSCLC tumor cells." (PMID 32316322, 2020). "Among the most significant genes we identified SKP2, IRF2 and MCM3, all related to tumor progression and metastases." (PMID 31533831, 2019). "The network includes genes that are cancer promoters and tumor suppressors such as FYN HSPA8, YWHAZ, LEPR and TGFBR2, IRF2, EP3000 respectively." (PMID 18811983, 2008). "Indeed, IRF2 is essential for the development and maturation of natural killer cells and acts as a CD8 T cell nexus to translate signals from inflammatory tumor microenvironments." (PMID 38589899, 2024). "Similarly, in a recent study with a tumor model, IFN-mediated activation of transcription factor IRF-2 has been reported to suppress the immune response." (PMID 36883950, 2023). "These phenotypes could be due to KRAS repressing the interferon regulatory factor 2 (IRF2), leading to high CXCL3 expression and the recruitment of myeloid‐derived suppressor cells to the tumor microenvironment." (PMID 32239503, 2020). "Nevertheless, considered together with other findings, whereas IRF-2 may be classified as an oncogene, these results are consistent with IRF-1 having tumor-suppressing potential." (PMID 29599126, 2018). "In the same work, it was also found that up-regulation of IRF-1, but not IRF-2, leads to better tumor differentiation, enhanced lymphocyte infiltration, smaller tumor mass, and longer survival." (PMID 29599126, 2018). "Our findings suggest that miR-302b may be a novel CRI regulating miRNA that inhibits CRI critical pathway and downstream cytokines expression through targeting ERBB4, IRF2 and CXCR4, resulting in decrease of tumor growth." (PMID 28467773, 2017). "Analysis of the mouse cd279 promoter regions by ChIP illustrated that after IFNβ and IFNΒCOL01 treatment, enrichment of irf2 increased in the promoter regions of the cd279 gene in −2000 to +2000 regions in RAW264.7 cells and in −2000 to 0, +1000 to +2000 regions in tumor-infiltrating CD11b+ cells." (PMID 38995014, 2024). "Analyses of mouse irf2 promoter regions by ChIP demonstrated that after IFNβ and IFNBCOL01 treatment, enrichment of pSTAT1 increased in the promoter regions of the irf2 gene in −2000 to +2000 regions in RAW264.7 cells, and in −2000 to 0, +1000 to +2000 regions in tumor-infiltrating CD11b+ cells." (PMID 38995014, 2024). "In addition, we show that the generated NK cells from the IRF2 knockdown cultures do not reach full NK cell functionality as they display impaired cytotoxicity against tumor target cells and reduced cytokine secretion upon cytokine stimulation." (PMID 36544762, 2022). "To further evaluate the relationship between IRF-2 and AMER-1 in GAC patients and xenografted tumor tissues in nude mice, we examined the expression levels of AMER-1 by immunohistochemical assay, using anti-AMER-1 antibody in the same TMA specimens and xenografted tumor tissues." (PMID 35115027, 2022). "ChIP-Seq assay showed that IRF-2 could directly activate AMER-1 transcription and regulate the Wnt/β-catenin signaling pathway, which was validated using IHC, in both tissue microarray and xenografted tumor tissues, western blot analysis, and cell function experiments." (PMID 35115027, 2022). "Genes of the antigen-processing machinery and regulation (IRF1, IRF2, NF-κB1, NF-κB2, NLRC5, TAP1, TAP2, TAPBP) were not significantly expressed throughout all of the analyzed tumor transcriptomes." (PMID 35892842, 2022).
tumor (continued). "When both IRF1 and IRF2 were absent, type I IFN treatment could not restore MHC I expression or reverse resistance to CPI, confirming the concept that type I IFN can induce IRF1 and restore immunogenicity of the tumor cells and host cytotoxic response to them." (PMID 39281881, 2024).
cancer (53 papers, 2008 to 2025). A tumor composed of atypical neoplastic, often pleomorphic cells that invade other tissues. "Interferon regulatory factor 2 (IRF2) is a constitutive transcription factor associated with the development of various cancers through the regulation of cancer cell growth, apoptosis, and drug resistance." (PMID 36980210, 2023). "The interferon regulatory factor 2 (IRF2) is a constitutive transcription factor associated with the development of various cancers by regulating the cancer cell growth, apoptosis, and drug resistance." (PMID 34658879, 2021). "What’s more, a recent study reports that loss of IRF2 leads to immune evasion of cancer cells through repressing MHC Class I antigen presentation and increasing PD-L1 expression." (PMID 34022918, 2021). "IRF2 is a constitutive transcription factor associated with the development of various cancers by regulating cancer cell growth, apoptosis, and drug resistance." (PMID 33735820, 2021). "Consequently, loss of IRF2 could render cancers both harder to see (loss of MHC I) and harder to kill (loss of caspase 7 and increased PDL-1)." (PMID 39281881, 2024). "While a therapeutic effect of anti-PD1 + poly(I:C) was still seen with these tumors, they were still significantly more resistant to CPI compared to the IRF2 KO cancer cells." (PMID 39281881, 2024). "Our study shows that a subset of cases within most types of cancers downregulates IRF2 and that this can allow cancers to escape immune control." (PMID 39281881, 2024). "Our major findings are that IRF2 expression was reduced in subsets of almost all human cancer types and that this reduction had functional consequences." (PMID 39281881, 2024). "Bioinformatics analyses of IRF2 and IRF2-dependent gene transcripts were performed for all human cancers in the TCGA RNAseq database." (PMID 39281881, 2024). "In turn, miR-18a belongs to the miR-17-92 cluster, which naturally inhibits cancer development because it stimulates the expression of IRF2 and thus regulates the immune response dependent on M1 macrophages and NK cells." (PMID 38473390, 2024). "Calreticulin, which plays a broad role as a chaperone for many ER proteins including MHC I, was only positively correlated with IRF2 expression in some cancer types." (PMID 39281881, 2024). "Transcriptomic analysis revealed that IRF2 expression was reduced in a substantial subset of cases in almost all types of human cancers." (PMID 39281881, 2024). "Similar to the role of PAX8 in renal development and ccRCC, IRF2 plays an important role in cancers originating from the plasma cell lineage." (PMID 37554444, 2023). "Low expression of IRF2, 4, 5, and 8 was resistant to most of the drugs or small molecules from Genomics of Drug Sensitivity in Cancer." (PMID 35012444, 2022). "We found that the IRF-2 expression level was significantly positively correlated with patients’ overall survival time (OS) (P < 0.001) and cancer-free survival time (DFS) (P = 0.014), indicating that higher IRF-2 expression correlated with longer DFS and OS." (PMID 35115027, 2022). "Frequent loss of IRF-2 leads to decreased MHC class I antigen presentation and increased PD-L1 expression in cancer, resulting in immune evasion." (PMID 35115027, 2022). "The TF interferon regulatory factor 2 (IRF2) has been reported to participate in cancer growth and immune cell function." (PMID 34185419, 2021). "Loss of IRF2 leads to immune evasion through decreased MHC class I antigen presentation and increased PD-L1 expression in cancers." (PMID 34738869, 2021). "IRF2 is reported to influence the occurrence and development of cancer via altering its target genes involved in cell proliferation, apoptosis, and metastasis." (PMID 33735820, 2021).
cancer (continued). "IRF2, which belongs to the interferon regulatory factor family of TFs, is mainly involved in immune responses and cancer processes." (PMID 34185419, 2021). "Lenvatinib treatment is a selection process of cancer cells, resulting in a stronger viability and tendency to develop malignancy, which promotes the expression of oncogene IRF2 and β-catenin." (PMID 33735820, 2021). "They reported that miR-18a-5p acts as an oncogene leading to OS cell proliferation and invasion, targeting and consequently inhibiting IRF2, which has been reported to act as a functional regulator in cancers." (PMID 33503899, 2021). "By using NGS technologies, somatic mutations in several novel cancer-related genes such as ARID1A (7.53%), HNF4α (0.88%), FAT4 (4.71%) and IRF2 (1.06%) have been identified and suggested to be associated with HCC." (PMID 31395065, 2019). "This review discusses the functions of IRF-1 and IRF-2 in human cancers, with a focus on the potential contribution of IRF-1 inactivation to human carcinogenesis and the future of IRF-1 as a therapeutic target." (PMID 29599126, 2018). "Among the top 10 DRGs identified for Korean (GSE24375), six genes are GC related (ESRRG, LIMS1, GATA3, GATA6, SOX9, POU2F1) and the other four are cancer related (IRF2, RGS3, MRPL36, FOSB)." (PMID 29745833, 2018). "This review focusses on current knowledge of the roles of IRF-1 and IRF-2 in human cancer, with particular attention paid to the impact of IRF-1 inactivation." (PMID 29599126, 2018). "The fact that IRF-2 expression was often elevated in cancer cells, and elevated IRF-2 levels would enhance NF-κB activity when delivered an activation, such as TNF-α." (PMID 28465494, 2017). "This pattern of expression is consistent with reports that IRF2 expression level increases with cancer progression." (PMID 21050451, 2010). "IRF1 and IRF2 were essential in regulating interferon activity, where the absence of IRF1 and the increase in IRF2 expression had been associated with aggressive traits in different types of cancer." (PMID 38999981, 2024). "Interferon regulatory factor-2 (IRF2) exerted antitumor effects in several human cancers." (PMID 36199790, 2022). "IRF2 regulation of GSDMD levels may represent a critical regulatory axis in cancer cell death, given that its loss in cancer leads to immune evasion and resistance to immunotherapy." (PMID 33840390, 2021). "IRF2 was dramatically increased in HCC compared to adjacent non-cancer liver tissues." (PMID 33735820, 2021). "Besides, IRF2 is reported to influence the occurrence and development of some cancers through proliferation, apoptosis and metastasis via altering its target genes." (PMID 30876449, 2019). "IRF2 is considered as one of the most desirable targets for cancer therapies." (PMID 28471447, 2017). "The mean cancer/normal ratio of IRF-2 mRNA expression was 9.26 (range, 2.99 to 20.84)." (PMID 28465494, 2017). "Against this baseline, loss of IRF2 clearly converted these cancers to being non-responders to CPI." (PMID 39281881, 2024). "KEGG analysis also showed that IRF-2 may affect several cancer pathways." (PMID 35115027, 2022). "Hence, IRF2 may regulate different signaling pathways to either promote or suppress the development of cancer." (PMID 33735820, 2021). "In the last two decades, the multifunctional IRF-2 in oncogenesis and altered expression in several human malignancies have been reported and this differential expression may influence clinical outcomes of cancer patients." (PMID 28465494, 2017). "The dedifferentiated phenotype relies on newly acquired dependencies on IRF2, BHLHE40, and ZNFX1, which represent rare pan-cancer dependencies." (PMID 37554444, 2023). "This included positive associations between losses in 1p36.32, 3p26.2, 4q35.2, 7p22.3 and 18q23 with the expression of the cancer-related genes CDKN11B, CRBN, IRF2, PRKAR1B and NFATC." (PMID 33945543, 2021).
cancer (continued). "By trans-element analysis from the set of altered enhancers, we successfully identified IRF2, RELA, NFATC2, etc., as essential TFs involved in cancer cell growth and migration, possibly via establishing oncogenic enhancer programs." (PMID 34294701, 2021). "IRF2, as an IFN regulatory transcription factor has vital implications in approaches to assess cancer progression and for immunotherapy by way of both positively regulating the MHC pathway and down regulating PD‐L1 expression." (PMID 32902917, 2020). "Other candidates, such as SMARCA1, KDM6B, IRF2, PLK4, and HUWE1, may well have functional relevance to cancer development in particular cancer types, and be worthy of further investigation." (PMID 40514689, 2025). "Similarly, systemic treatment with a type I IFN inducer, poly I:C, reversed resistance of IRF2 null cells to CPI in vivo and this salutatory effect was also dependent on IRF1 in the cancer cells." (PMID 39281881, 2024). "However, in a previous forward genetic screen, we found that IRF2 was also a transcriptional activator of multiple MHC I pathway genes, at least in mouse dendritic cells and some cancer cell lines." (PMID 39281881, 2024). "Different from what was seen in mouse dendritic cells, CD274 transcripts were not negatively correlated with IRF2 mRNA but rather had a positive correlation in some cancers." (PMID 39354629, 2024). "Although IRF2 is not catalogued in Census nor Intogen, functional studies have identified it as a cancer suppressor gene in HCC31." (PMID 34824211, 2021). "Binding motifs for many essential TFs, such as RXRA, NFE2L2, ESRRA, IRF2, RELA, ESRRA, SOX2, and SMAD2/3, key TFs that mediate TGFβ signaling in epithelial-mesenchymal transition (EMT) and cancer metastasis, were enriched in common gained or LNC-specific gained enhancers, with some overlapping TFs." (PMID 34294701, 2021). "IRF2 is a functional antagonist of IRF1 and may act as an oncogene, promoting the formation and progression of cancer." (PMID 27806724, 2016). "Similarly, it would be on interest to determine whether a cancer’s levels of IRF1 and IRF2 might be biomarkers for tumors that might benefit IFN treatment to improve the efficacy of CPI." (PMID 39281881, 2024). "Recently, cancer cells subjected to selection for increased or decreased expression of MHC-I have been subjugated to forward genetic screenings, identifying a substantial number of new genes that are able to regulate MHC-I antigen presentations, including IRF2, PBAF, PRC2, and SPPL3." (PMID 37256225, 2023). "The correlation between IRF2 and Gasdermin D (GSMD) expression was weak or absent in a number of cancers." (PMID 39281881, 2024).
infection (21 papers, 2010 to 2026). The state of being infected such as from the introduction of a foreign agent such as serum, vaccine, antigenic substance or organism. "Infection with L. monocytogenes causes H3K18 deacetylation of many genomic proteins in colon cells, including SMAD1, IRF2, SMARCA2, and CXCL12." (PMID 35572672, 2022). "On day 3 after infection, when the most severe symptoms in both models appear, the combination of antibodies against IRF2 and CD14 resulted in the detection of a significantly increased monocyte population after E. histolytica infection." (PMID 36010615, 2022). "mRNA and protein expression levels of ZIKV and IRF2 were measured at 12, 24, 48 and 72 h-post-infection (hpi) by RT-qPCR and western blots." (PMID 34930359, 2021). "As shown in, ZIKV can steadily replicate in A549 cells, and compared with the uninfected control, IRF2 expression is gradually increased from 12 to 72 h post-infection." (PMID 34930359, 2021). "During early infection, L. major-infected DCs exhibited a distinct type-I IFN-associated transcriptomic signature, including the upregulation of IRF2, IRF9, STAT1/2, and IFNAR." (PMID 31608064, 2019). "IRF-2 expression was decreased at 4 and 12 weeks after infection in comparison with the saline controls." (PMID 29259694, 2016). "The results also suggested that IRF3 could be activated to a greater extent after poly(I:C) stimulation and SCRV infection in host cell than after the administration of IRF2 and IRF6." (PMID 29755465, 2018). "Therefore, we determined kinetics of IFNβand IRF2 expression during MHV68 infection in the spleen of wildtype, IFNAR1-/-, and IRF2-/- mice." (PMID 22114555, 2011). "Importantly, in IRF2-/- mice M2 transcript expressed by MHV68 increased precisely to the level observed in ISREΔ1 infection, while M3 and M9 expression efficiency were unaltered." (PMID 22114555, 2011). "The higher resistance of PANC-1 cells to 17D infection, compared to MIA PaCa-2 cells, may be attributed to the increased expression of IRF2 and IRF7, which regulate the interferon α and γ genes in this cell line." (PMID 39852819, 2025). "We retrieved lists of the known targets of NF-kB/p65, STAT1, STAT2, IRF2, and IRF3 and extracted from these lists genes that were differentially expressed either during infection in Dicer WT or Dicer N1 cells, or between mock-infected Dicer WT and Dicer N1 cells." (PMID 38287188, 2024). "IRF2 in combination with CD14 best distinguishes the Ly6Chi population in the ameba and listeria model from the population in naïve mice at least on day 3 post infection, the peak of liver pathology in these models." (PMID 36010615, 2022). "In line with IFNRT, also KO of IRF9 again prevented the upregulation of IRF7 and also IRF2, but peculiarly, different from in the infection setting it did not lead to augmentation of IRF1 induction." (PMID 34685580, 2021). "Furthermore, 2-D08 treatment coupled with GCRV challenge resulted in higher IRF2 and PKR level during infection in comparison to those of CIK cells infected with GCRV only." (PMID 29069722, 2017). "This indicates that the immune modulatory functions of IRF2 are not essential for an effective response to MHV68 infection." (PMID 22114555, 2011). "In another study, a coordinated down-regulation of MHC I pathway-related genes during the later stages of infection was demonstrated, including the down-regulation of interferon-regulatory factor (irf)-1, independent of interferon-α, interferon-γ, and irf-2 expression." (PMID 36090977, 2022). "Interestingly, before infection, the expression levels of many of these master regulators (e.g., REL, NFKB1, RELB, IRF2, IRF9) were different across the three species, while post-infection, their expression converged to practically the same level, regardless of species." (PMID 21187902, 2010).